MTOR (mechanistic target of rapamycin kinase)
Diseases named in the same sentence as MTOR in open-access papers (continued):
Sharing a sentence is not in itself a finding about the gene and the disease.
cancer (continued). "Some significant pathways activated and deactivated in cancer cells include PI3K/Akt, mTOR, AMPK, and MAPK." (PMID 37444478, 2023). "In a broader context, the intricate interplay between the mTOR axis and MET biology underscores the pivotal role of translational regulation in governing MET expression within the realm of cancer." (PMID 37760640, 2023). "The signaling pathways in various cancers were PI3K, AKT, mTOR, MAPK, ERK, JAK, STAT3, EGFR, AMPK, ERK1/2, S473AKT, Ras, ErbB2/ErbB3, JNK1/2." (PMID 37743502, 2023). "Cancer cells frequently undergo metabolic rewiring, driven by oncogenic pathways such as HIF, Wnt, mTOR, and NF-κB, to support the increased proliferative rate as tumours develop and progress." (PMID 37720350, 2023). "Resveratrol exerts anti-cancer activity through various molecular mechanisms, including the PI3K/Akt, STAT3/5, MAPK, AMPK/mTOR, SIRT1/NF-κB, and PGC-1α signaling pathways." (PMID 38136176, 2023). "Taken together, apoptosis induction and cell proliferation inhibition via PI3K/AKT/mTOR and Bax/Bcl-2/Caspase-3 pathway are promising evidence to support B. coagulans MZY531 as a potential therapeutic agent for cancer." (PMID 37705007, 2023). "The main roles of circRNAs in regulating cancer processes are due to their regulatory roles in essential oncogenic pathways, including MAPK, PI3K/AKT/mTOR, and Wnt, which are influenced by various circRNAs." (PMID 37833993, 2023). "Some autophagy regulators, such as the best-known mTOR inhibitors rapamycin and its derivatives (temsirolimus and everolimus), chloroquine (CQ), and hydroxychloroquine (HCQ), are also used in cancer treatment." (PMID 36994671, 2023). "It has the same inhibitory effect as PI3K in terms of kinase inhibition activity; therefore, XIN-10 has strong potential as a dual inhibitor of PI3K/mTOR, and the development of dual inhibitors of PI3K/mTOR can serve as a reference for cancer and research." (PMID 37834269, 2023). "We also considered separately a fraction of 710 genes included in six major cancer-related molecular pathways (AKT, mTOR, EGFR, and Notch, WNT, and Hedgehog pathways) that form two non-overlapping regulatory axes." (PMID 37174700, 2023). "We have previously shown that PPRHs are a valuable tool for gene silencing of relevant cancer targets such as dihydrofolate reductase, survivin, BCL2, TOP1, mTOR, MDM2, and MYC." (PMID 37108234, 2023). "In this study, we analyzed in detail the evolutionary dynamics of two major cancer axes: Notch/WNT/Hedgehog and AKT/mTOR/EGFR." (PMID 37174700, 2023). "Previous studies have shown that the PI3K/AKT/mTOR pathway modulates cell cycle, apoptosis, autophagy, angiogenesis, EMT, and chemoresistance in cancers." (PMID 37644594, 2023). "In comparison with SNHGclusterB, SNHGclusterA was enriched in cancer-related pathways such as ERBB, mTOR and MAPK; immune-related pathways such as TOLL-like and NOD-like pathways etc. using KEGG signatures." (PMID 36159816, 2022). "Enhanced AKT1 expression in cancer cells leads to cell proliferation and cell cycle through various downstream effectors, including cyclin D1, GSK-3, mTOR, etc.." (PMID 35646655, 2022). "Previous studies show that cancer stem cells have an important role in patient relapse, with PI3K/AKT/mTOR as well as the Sonic Hedgehog signaling pathway being reactivated in the process." (PMID 36077529, 2022). "Important signaling pathways are mediated by hedgehog (HH), Notch, wigless (Wnt), hippo (Salvador-Warts-Hippo), JAK/STAT, TRPV4, cAMP/cGMP, mTOR and platelet-derived growth factor (PDGF) for intercellular communications between cancer cells." (PMID 36498831, 2022).
cancer (continued). "As a transcription factor, SOX9 acts as a pleiotropic factor by regulating several key signaling pathways in cancers, such as the Wnt/β-catenin, TGFβ/Smad, PI3K/AKT, and mTOR signaling pathways." (PMID 35563098, 2022). "The cross talk between the cyclinD1-CDK4/6-pRb axis and PI3K/AKT/mTOR pathway has always been regarded as more obvious in hormonal receptor-positive and HER2-positive cancers, as ER can directly target cyclin D1 transcriptionally and activate CDK4/6-pRb." (PMID 36387174, 2022). "AMPK activation leads to inhibition of mTOR phosphorylation at serine 792 and promotes the formation of the TSC1/2 complex, which facilitates apoptosis in cancers." (PMID 36012522, 2022). "Different mechanisms can explain the anti-cancer activity of Ivermectin, including inhibition of MDR, modulation of Akt/mTOR, and Wnt/TCF signaling pathways, inactivation of PAK-1 expression, among others." (PMID 36139522, 2022). "From cancer studies, it was established that eEF1A proteins can promote cell growth and proliferation by serving as an upstream activator of PI3K/AKT/mTOR and/or PI3K/AKT/STAT3 pathways." (PMID 36123349, 2022). "The mTOR pathway regulates FANCD2, which leads to cancer cells’ resistance to DNA double-strand breaks." (PMID 35402264, 2022). "Circular RNA ciRS-7 acted as a sponge of miR-7, upregulating several oncogenes (mTOR, EGFR, PIK3CD) to promote the progression of cancers in which high ciRS-7 expression correlated with worse prognosis and miR-7 acted as tumor suppressor." (PMID 35550610, 2022). "Also, mTOR may directly increase pre-cancer/cancer cell growth." (PMID 36052376, 2022). "As observed in the cancer cell-DRG coculture system, mTOR knockdown in cancer cells decreased the cancer cell invasion index and DRG axon growth index." (PMID 35449152, 2022). "Using the human endometrial cancer cell line MFE-280 as a model, researchers found that inhibiting mTOR/PI3K/Akt signaling led to triggering apoptosis and halting cell cycle progression with substantial anti-cancer effects." (PMID 35986346, 2022). "Taken together, these results show that inhibition of endogenous H2S decreases the expression of p-PI3K, p-mTOR, and p-AKT, indicating that they inhibit the proliferation, invasion, and migration of human BC cancer cells via blocking the PI3K/AKT/mTOR pathway." (PMID 35807290, 2022). "Commonly, NGF is an upstream regulator of the mTOR pathway and few studies have shown that mTOR can regulate the expression of NGF in cancer cells." (PMID 35449152, 2022). "First, we investigated the role of key genes in all well-known cancer-related pathways, as the following: TSC/mTOR, RTK, RAS/MAPK, PI3K/AKT, Hormone ER, Hormone AR, EMT, DNA Damage Response, Cell Cycle, Apoptosis pathways." (PMID 35111402, 2022). "The aberrant Wnt/β-catenin, mTOR, and MAPK signaling pathways facilitate cancer cell proliferation and differentiation." (PMID 35800060, 2022). "The results showed that many cancer-related pathways were significantly (p < 0.01) enriched such as MAPK signaling, mTOR signaling, and AMPK signaling." (PMID 35147498, 2022). "Interestingly, the high-risk score group also comprised significant enrichment of unfavorable cancer-related hallmark gene sets, such as “ANGIOGENESIS”, “E2F_Target”, “IL2_STAT5 signaling”, “IL6_JAK_STAT3 signaling”, “MTORC1 signaling”, “MYC_TARGETS_V1” and “PI3K_AKT_MTOR signaling”." (PMID 37304008, 2022). "Similarly, Fdb treatment with a suboptimal dose can reduce drug toxicity in both normal and cancer cells, but the cells showed a difference in their ability to induce the mediators of cell survival, such as Beclin-1 (anti-apoptosis), found downstream of mTOR and LC3B." (PMID 35323219, 2022). "Mammalian target of rapamycin (mTOR) is another important effector in PI3K pathway and plays critical roles in cancer cell growth." (PMID 35372044, 2022).
cancer (continued). "The carcinogenesis and malignant progression of various malignant tumors are closely related to EMT, which can be regulated by PI3K/AKT/mTOR signaling pathway." (PMID 35757470, 2022). "The efficacy of the mTOR inhibitor sirolimus, and targeted therapies that block the Ras/BRAF/MEK/ERK1/2 and PI3KCA/AKT/mTOR pathways in cancer and complex VAs, further supports a role of ESC-like cells in the pathogenesis of these conditions." (PMID 35574555, 2022). "UBE2T is also involved in activating oncogenic signaling pathways, such as the mTOR and TNFA signaling pathways, which are known to modulate cancer growth and progression." (PMID 36338541, 2022). "Metformin leads to cell cycle arrest and reduces cell growth, proliferation, protein synthesis and the cancer stem cell number in the tumor and its microenvironment by activating the AMPK pathway and inhibiting the mTOR pathway or PI3K/AKT pathway." (PMID 35740547, 2022). "When PD-1 binds to its ligand, PD-L1, the two recruits, SHP2, generate inhibitory signals and inhibit the PI3K/AKT/mTOR and RAS/MEK/ERK1/2 pathways, thereby inhibiting the activation of T cells and helping the immune escape of cancer cells." (PMID 36059800, 2022). "Although several drugs have been successful developed in treating cancer by interfering with MAPK/ERK and PI3K/AKT/mTOR pathways, drug resistance often occurs and limits their durable clinical benefit." (PMID 35372044, 2022). "PI3K-Akt-mTOR activation actively participates in key hallmarks of NSCLC, including sustained cancer growth, apoptosis resistance, angiogenesis, cancer invasion and metastasis and insensitivity to therapies." (PMID 35717530, 2022). "Low IGF-1 levels result in the inhibition of PI3K/Akt/mTOR system and of the synthesis of vascular endothelial growth factor (VEGF), which are involved in angiogenesis, cancer cell proliferation, and survival." (PMID 36139562, 2022). "In this study, we found stromal cell-derived EREG not only activates Akt/mTOR, MEK/ERK pathways, signaling branches downstream of EGFR, but also generates a profound impact on genome-wide expression of cancer cells." (PMID 36202915, 2022). "MEG3 governed several cancer-relevant signal transduction pathways, such as TGF-β, PI3K/Akt, Notch, mTOR, and Wnt/β-catenin signaling cascades." (PMID 35656022, 2022). "There is some evidence that irradiation resistance in various cancer cell types can be reduced in vitro and in in vivo xenograft models of cancer by dual targeting of PI3K and mTOR." (PMID 36555391, 2022). "C1P facilitates cell growth, migration, differentiation and survival via the PI3K/AKT/mTOR, glycogen synthase kinase-3β or Ras/Raf/ MEK/ERK pathways, which are well-known to have tumor-promoting roles in human cancer 26, 29, 30, 53-57." (PMID 35982909, 2022). "RASAL2 also suppresses cancer progression via the RAS-ERK pathway 22, phosphoinositide 3-kinase (PI3K)/AKT/mechanistic target of rapamycin (mTOR) signaling pathway 7, nuclear factor (NF)-κB pathway 7, and ERK/mitogen activated protein kinase (MAPK) pathway." (PMID 35844783, 2022). "Because mTOR is a downstream target of EGFR and MET signaling, it is a promising target for cancer treatment." (PMID 36293326, 2022). "Among these eight cancer targets, BCL-2, Topoisomerase, PTK, mTOR and PI3K docking studies showed the best binding energy inhibition constant and ligand efficiency.Thus, it concludes lupeol is one of the significant anticancer phytodrugs." (PMID 36518133, 2022). "We analyzed CRGs involved in well-known cancer-related signaling pathways (apoptosis, cell cycle, DNA damage response, EMT, hormone AR, hormone ER, PI3K/AKT, RAS/MAPK, RTK, and TSC/mTOR)." (PMID 36387247, 2022).
cancer (continued). "Similar response rates were observed with the dual PI3K/mTOR inhibitors gedatolisib and bimiralisib (PQR309) in patients with various advanced-stage cancers." (PMID 35887235, 2022). "The network results demonstrated that seven anti-HCC core targets (CASP3, EGFR, ERBB2, mTOR, MMP9, HIF1A, and PPARG) followed the pathways in cancer (degree 7)." (PMID 35959427, 2022). "These lncRNAs significantly target the key downstream molecules of cancer-related pathways, namely the Wnt/β-catenin and PI3K/Akt/mTOR pathway." (PMID 35448163, 2022). "CHE was found to downregulate the expressions of MMP-2 and MMP-9 through the PI3K/Akt/mTOR signaling pathway and change the cytoskeleton structure by reducing p-FAK, which inhibited the metastasis and invasion of cancer in a dose-dependent manner." (PMID 35721116, 2022). "Multivariate Cox regression showed that seven cancer-essential FRGs (ISCU, NFS1, MTOR, EIF2S1, HSPA5, AURKA, and RPL8) were significantly associated (p<0.05) with OS." (PMID 35756689, 2022). "Changes in the mTOR expression and LC3B were found in patients with partial response, verifying the involvement of the biological factors in the behavior of aggressive cancers." (PMID 35877414, 2022). "Potential anti-cancer drugs that inhibit PI3K and mTor at the same time showed greater efficiency and reduced the likelihood of inducing drug resistance." (PMID 35215333, 2022). "UCK2 is essential for maintaining the stability of mTOR, and downregulation of UCK2 can specifically inhibit mTOR signalling pathway-related metabolic reprogramming of cancer cells." (PMID 36447138, 2022). "On the other hand, SRC, CASP3, EGFR, ERBB2, mTOR, MMP9, and HIF1A followed the proteoglycans in cancer." (PMID 35959427, 2022). "The action behind anti‐cancer effects of metformin is mainly a result of AMPK activation, mTOR inhibition, regulation of insulin and other AMPK‐independent pathways." (PMID 36052760, 2022). "The PKD2 pro-proliferative function is mediated by inducing the PI3K/AKT/mTOR signaling pathway via GOLPH3, an oncogene that stimulates cancer cell growth by regulating this signaling cascade." (PMID 35805075, 2022). "Meanwhile, some pathways closely related to cancers such as Notch signaling pathway, TGF-beta signaling pathway, PI3K-Akt signaling pathway, mTOR signaling pathway, and Wnt signaling pathway were enriched in the high-risk group." (PMID 36561981, 2022). "Recently, PI3K/Akt/mTOR and Ras/Raf/MEK/ERK signaling pathways have also been recognized as a new strategy for cancer therapy." (PMID 36506551, 2022). "Another mTOR inhibitor, ridaforolimus (AP23573, MK-8669), was combined with bevacizumab and administered to 17 patients with advanced cancers, including two patients with pancreatic adenocarcinoma." (PMID 36077529, 2022). "mTOR pathway plays a critical role in tumorigenesis and cancer progression, and a potential correlation has been identified between MYBL2 and mTOR in Arabidopsis." (PMID 35557985, 2022). "In research on many anti-cancer drugs, the MAPK/mTOR/p70S6K and Akt pathways or the PI3k-Akt pathway are involved in the regulation of pAKT expression and contribute to inhibition of tumor growth." (PMID 35741311, 2022). "In these cancers, the PI3K/Akt/mTOR pathway plays a central role in survival, proliferation, migration and metabolic rewiring, wherein it was reported to be hyperactivated." (PMID 36287116, 2022). "Further, we found that Hsa-miR-22-3p, Hsa-miR-184, and Let-7b-5p functionally converge on WNT/βcatenin and mTOR/AKT signaling axes, known cancer therapy resistance signals." (PMID 35461372, 2022). "Preclinical data have indicated a significant improvement and synergy in the anti-cancer drug response in TNBC when EGFR and mTOR inhibitors are combined compared with single therapeutic approaches." (PMID 36428475, 2022).
cancer (continued). "It is of interest to document the molecular docking analysis data of lupeol with different cancer targets such as Caspase- 3, BCL-2, Topoisomerase, PTK, mTOR, H-Ras, PI3K, AKT." (PMID 36518133, 2022). "We previously utilized EAC cell lines and an EAC xenograft model to investigate the cancer inhibitory effects of C-PAC via the PI3K, MAPK, AKT and MTOR signaling cascades as well as cell death induction through apoptosis, autophagy and necrosis." (PMID 35267943, 2022). "Dual PI3K/mTOR inhibitors that inhibit PI3K class I isoforms, mTORC1, and mTORC2, have shown promise in cancer-related clinical trials." (PMID 36683775, 2022). "In many tumor types, the SHH signaling pathway has been reported to crosstalk with other critical molecular signaling pathways involved in cancer, such as RAS/RAF/MEK/ERK, PI3K/AKT/mTOR, EGFR, and Notch." (PMID 36034794, 2022). "Members of the FGFR family were upregulated in the HPV-positive group of the four cancers, implying combined inhibition of FGFR and mTOR for targeted therapy." (PMID 35392231, 2022). "HIF-1α exerts an important function in cellular adaptation to hypoxia by activating multiple cancer signaling pathways, including phosphoinositide 3-kinase (PI3K)/Akt/mammalian target of rapamycin (PI3K/Akt/mTOR) and ERK/MAPK." (PMID 36080483, 2022). "ERRα antagonist destroys mitochondrial function, inhibits lactic acid utilization, damages the activity of cancer cells, and increases the activity of PI3K/mTOR inhibitor." (PMID 35800058, 2022). "Therefore, it represents a revolutionary landscape during cancer progression that could be useful for developing new and improved therapeutic strategies targeting alterations in cancer cell metabolism, such as the deregulated mTOR and PI3K pathways." (PMID 35745875, 2022). "A ketogenic diet targets glucose metabolism in cancer cells, inhibits the IGF-1 and PI3K/AKT/mTOR pathways, and suppresses CC, muscular wasting, and tiredness." (PMID 35565236, 2022). "Taken together, EGFR, PI3K/Akt, and mTOR signal pathways can control SREBP-1 expression and activation to regulate its downstream pathways in cancers." (PMID 35912181, 2022). "Together, fatostatin mainly regulates the activation of SREBP-1/2 to block different cancer progressions, while it also regulates the accumulations of PUFAs and the PI3K/Akt/mTOR pathway." (PMID 35912181, 2022). "Important signaling pathways, such as NF-κB, PI3K/Akt/mTOR, Notch 1, Wnt/β-catenin, and YAP, have been considered as therapeutic targets for patients with cancer." (PMID 35517785, 2022). "So, the current study targets the AKT/mTOR signaling pathway, downstream of ITZ, investigates the anti-cancer effect of monotherapy using ITZ and another drug each, as well as the two in combination, in TNBC cells." (PMID 35517785, 2022). "The MAPK and AKT/mTOR pathways are generally disrupted in HCC, while the Wnt pathway, a canonical cancer-related pathway, is up-regulated in many cases of early HCC." (PMID 35629368, 2022). "In conclusion, this study demonstrated that 4AAQB inhibited both cancer growth and angiogenesis in vitro by inhibiting the activation of the VEGFR2, PI3K/Akt, mTOR, and ERK pathways." (PMID 35163369, 2022). "Moreover, recent investigations showed that targeting mTOR could be considered as cancer therapy." (PMID 36428613, 2022). "This stress-inducible protein accumulates as a result of autophagy inhibition and is known to be involved in cancer progression by several means, including the interaction with NRF2, mTOR and NFkB." (PMID 35681760, 2022). "eATP (≥1000 μM) was found to inhibit mTOR via upstream blockade of phosphatidylinositol-3-OH kinase/protein kinase B (PI3K/AKT) and activation of AMP kinase (AMPK) in cancer cells." (PMID 36430925, 2022). "The parallel interaction between mTOR and PI3K signaling pathways implies their similarity in performing regulatory roles in cell proliferation and apoptosis needed for cancer survival and proliferation." (PMID 35327484, 2022).